THBD (thrombomodulin)
Diseases named in the same sentence as THBD in open-access papers (continued):
Sharing a sentence is not in itself a finding about the gene and the disease.
glioma (6 papers, 2014 to 2024). A benign or malignant brain and spinal cord tumor that arises from glial cells (astrocytes, oligodendrocytes, ependymal cells). "Our findings reveal that the THBD+ macrophage subpopulation is closely associated with hypoxia in glioma, exhibiting significantly higher infiltration in tumours compared to non‐tumour tissues." (PMID 38809929, 2024). "To investigate the impact of THBD+ macrophages on gliomas, we initially utilized bulk sequencing data to assess the infiltration level of THBD+ macrophages across various glioma types." (PMID 38809929, 2024). "Silencing THBD expression leads to a notable reduction in the proliferation and metastasis of glioma cells." (PMID 38809929, 2024). "In summary, the findings suggest a positive correlation between the presence of THBD+ macrophages and the aggressiveness of gliomas, with this particular subtype facilitating the proliferation, migration and invasion of malignant cells within gliomas." (PMID 38809929, 2024). "The findings indicated a notably elevated infiltration level of THBD+ macrophages in the most malignant gliomas, with the infiltration score positively correlating with glioma malignancy." (PMID 38809929, 2024). "Presently, there is a paucity of literature exploring the involvement of THBD in tumours, particularly in the context of gliomas." (PMID 38809929, 2024). "In our study, we first discovered that hypoxia could upregulate THBD expression in gliomas cells, and knocking down THBD in macrophages inhibited the proliferation, migration and invasion abilities of cocultured gliomas cells." (PMID 38809929, 2024). "Therefore, further studies are warranted to expand the experimental scale in order to verify the relationship between THBD+ macrophages and the progression of glioma." (PMID 38809929, 2024). "We hypothesize that THBD+ macrophages are involved in the malignant progression of glioma." (PMID 38809929, 2024).
preeclampsia (6 papers, 2012 to 2024). Preeclampsia is a hypertensive disorder of pregnancy that is characterized by new-onset hypertension with proteinuria presenting after 20 weeks of gestation, and depending on mild or severe forms may initially present with severe headache, visual disturbances, and hyperreflexia. "Preeclampsia is associated with the increased t-PA, thrombomodulin, TAT, PAI-1, TF, TFPI1, and TFPI2 levels, decreased fibrinogen, antithrombin III, and PAI-2 levels, and increased fibrinolysis (e.g., D-dimer) compared to the normotensive controls." (PMID 37238908, 2023). "Thrombomodulin as a marker of endothelial injury in preeclampsia was associated with severity of disease and may be valuable in risk-stratifying women with preeclampsia." (PMID 36311221, 2022). "Circulating concentrations of thrombomodulin were increased in women with preeclampsia with two or more end-organ complications compared with women with preeclampsia without end-organ complications." (PMID 36311221, 2022). "Plasma samples taken at inclusion after diagnosis (preeclampsia cases) or at admission for delivery (normotensive controls) were analyzed with ELISA for syndecan-1, hyaluronic acid and thrombomodulin and compared between groups." (PMID 36311221, 2022). "Seven studies have shown increased circulating concentrations of thrombomodulin in women with preeclampsia compared with normotensive controls." (PMID 36311221, 2022). "Future prospective studies are necessary to conclude if thrombomodulin is a valuable biomarker for progression of disease in women with preeclampsia." (PMID 36311221, 2022). "Women with preeclampsia with two or more end-organ complications (n = 13) had increased plasma concentrations of thrombomodulin (5.46 ng/ml, IQR 4.85–7.83 vs." (PMID 36311221, 2022). "Plasma concentrations of thrombomodulin have been shown to be increased in gestational weeks 24 and 32 before onset of disease in women that later developed preeclampsia compared to women with normotensive pregnancies." (PMID 36311221, 2022). "The aim of this study was to investigate plasma concentrations of syndecan-1, hyaluronic acid and thrombomodulin in preeclampsia of different severity." (PMID 36311221, 2022). "Furthermore, the investigation identified a number of genetic variants in the genes of ADAMTS13, C3, CFH, CFB, thrombomodulin, MBL2, and MASP2 that were significantly linked with the occurrence of preeclampsia, according to the results of analyses A and B." (PMID 38673014, 2024). "In uteroplacental thrombosis, which is one of the major mechanisms of preeclampsia, several thrombotic and fibrinolytic factors including circulating soluble thrombomodulin (TM) and tissue plasminogen activator (tPA) were found to be elevated in PE and correlated with the severity of proteinuria." (PMID 33616216, 2021). "Our research adds to current knowledge by demonstrating that plasma concentrations of thrombomodulin increase by number of end-organ complications in preeclampsia when compared to women with preeclampsia without end-organ complications." (PMID 36311221, 2022). "One study investigated differences in thrombomodulin concentrations in preeclampsia with severe features (definition of severe features not further described) versus preeclampsia without severe features and did not detect any differences in plasma concentrations of thrombomodulin between groups." (PMID 36311221, 2022).
septic shock (6 papers, 2017 to 2025). Shock caused by infection; frequently caused by gram negative bacteria, although some cases have been caused by other bacteria, viruses, fungi, and protozoa; characterized by fever, chills, tachycardia, tachypnea, and hypotension. "In patients with septic shock, high plasma levels of soluble thrombomodulin (>10 ng/mL) have been associated with worse organ dysfunction and mortality." (PMID 39259541, 2024). "Thus, an exploratory broad phenotypic and functional analysis of circulating immune cells and mediators were carried out to better understand the role of the immune system in a subgroup of septic shock patients with endotheliopathy defined by increased levels of soluble thrombomodulin (sTM)." (PMID 41425588, 2025).
thrombotic microangiopathy (6 papers, 2017 to 2026). The syndromes of microangiopathic hemolytic anemia, thrombocytopenia, and variable signs of organ impairment, due to platelet aggregation in the microcirculation. "Human endothelial C receptor (EPCR)and human thrombomodulin (TBM) are two additional genes that can be knocked in to stop microscopic blood clots (thrombotic microangiopathy)." (PMID 41451219, 2025). "Recent studies have also identified mutations in diacylglycerol kinase-ε (DGKE), thrombomodulin (THBD, CD141) in thrombotic microangiopathies (TMAs) including aHUS." (PMID 28056875, 2017). "The complexity of coagulation, involving intricate interactions between various factors, is further complicated in the xenotransplantation context, particularly by abnormal pig vWF interactions, inefficient pig thrombomodulin, thrombotic microangiopathy, and consumptive coagulopathy." (PMID 39404060, 2025). "The higher maximum soluble thrombomodulin and lower minimum hematocrit may suggest the feature of thrombotic microangiopathy." (PMID 38529277, 2024). "Moreover, in earlier attempts to alleviate molecular incompatibilities in the coagulation cascade, transgenic expression of thrombomodulin (TBM), endothelial protein C receptor (EPCR), and CD47 minimized the thrombotic microangiopathy (TMA) that led to early graft failure." (PMID 41451219, 2025).
atypical hemolytic-uremic syndrome (5 papers, 2012 to 2023). "A variant of the THBD gene (p.D486Y) was reported as a causative mutation of atypical hemolytic uremic syndrome (aHUS), leading to dysregulation of complement activation." (PMID 34326846, 2021).
leukemia (5 papers, 2014 to 2024). A malignant (clonal) hematologic disorder, involving hematopoietic stem cells and characterized by the presence of primitive or atypical myeloid or lymphoid cells in the bone marrow and the blood. "For the subpopulation with leukemia, the baseline use of recombinant thrombomodulin in 2010 was already high at 21.5% (95% CI 20.0%-23.1%) and further increased to 47.3% (95% CI 45.7%-48.9%) in 2017." (PMID 33225103, 2020). "Another example is the higher use of recombinant thrombomodulin in patients with leukemia, which is seen because the Japanese guidelines recommend its use, again on the basis of expert opinion." (PMID 33225104, 2020). "Taken together, these data suggest an important cancer participation of an altered expression of miR-650 through 22q11.2 alterations by targeting different TSG, such as PER2 in leukemias and lymphomas, THBD in thyroid cancer, and both of them plus STAT5 in BRCA." (PMID 33086498, 2020).
liver cirrhosis (5 papers, 2011 to 2024). "Herein, we report a case of acute portal thrombosis associated with liver cirrhosis and treated with a recombinant form of soluble thrombomodulin (thrombomodulin alpha, TM-α) in combination with antithrombin III." (PMID 32328109, 2020). "Increased ETP in patients with cirrhosis of the liver, including severe disease, has a hypercoagulable status if thrombin generation is affected by the addition of thrombomodulin." (PMID 34066706, 2021). "Similar to the prothrombin-antithrombin balance, we reckon with the possibility that the decrease of the factor V is compensated for by the decrease of the delimiting factors protein C and protein S. This is supported by the finding of thrombomodulin resistance in liver cirrhosis patients." (PMID 28472132, 2017). "In a monocentric prospective study, including 260 patients with liver cirrhosis, they measured thrombin generation using ST Genesia Thrombin Generation System without and with thrombomodulin (TM)." (PMID 34066706, 2021).
Obesity (5 papers, 2019 to 2024). Accumulation of substantial excess body fat. "The reduction in protein C (PC), activated PC, soluble thrombomodulin (TM), and soluble E-selectin levels a year after Roux-en-Y gastric bypass surgery suggests a compensatory upregulation of PC during obesity." (PMID 36982743, 2023). "Accordingly, S1PR3, IQCG, and TF are common in HCL, aging, and CVD; ACSL1, THBD, and HNF4A are repeated in HTN, obesity, and CVD." (PMID 36035865, 2022). "Taken together, we conclude from these results that the deleterious effect of dietary beef tallow on disorders connected to obesity may be triggered by impaired fibrinolysis (downregulation of the PLAU gene) and increased coagulation (increased expression of F3 and decreased expression of THBD)." (PMID 31756991, 2019).
pancreatic cancer (5 papers, 1994 to 2025). "An early study investigating the haemostatic balance in pancreatic cancer found that the coagulation inhibitors antithrombin III, heparin cofactor II, protein C, free protein S, and thrombomodulin were significantly decreased during the progression of pancreatic cancer after diagnosis." (PMID 30314362, 2018). "To emphasize, although this was only proven in pancreatic cancer, antithrombin III, heparin cofactor II, protein C and S, and thrombomodulin levels decline as the disease progresses." (PMID 36314077, 2023).
psoriasis (5 papers, 2018 to 2025). An autoimmune condition characterized by red, well-delineated plaques with silvery scales that are usually on the extensor surfaces and scalp. "For the regulatory DC transcriptome, the proportion of regulatory semimature DCs expressing regulatory DC markers of BDCA-3 (THBD) and DCIR (CLEC4A) was increased in posttreatment psoriasis lesional skin compared to pretreatment psoriasis lesional skin." (PMID 37781383, 2023). "Notably, the effect of the environment on the same disease can be mediated through several distinct subfunction proteins (e.g., THBD and CD2 mediate psoriasis)." (PMID 29689083, 2018).
respiratory failure (5 papers, 2021 to 2026). The significant impairment of gas exchange within the lungs resulting in hypoxia, hypercarbia, or both, to the extent that organ tissue perfusion is severely compromised. "Interestingly, thrombomodulin levels were higher in children on ECMO for non-respiratory failure compared to those for primary respiratory indications." (PMID 39409009, 2024). "Soluble thrombomodulin is an attractive candidate biological marker for respiratory failure and ARDS because thrombomodulin, an anti-thrombotic agent found in the endothelial cell surface, is cleaved into its soluble form in response to local endothelial damage." (PMID 34344416, 2021).
Thrombocytopenia (5 papers, 2022 to 2026). A reduction in the number of circulating thrombocytes. "While blood transfusions have been reported to be effective for managing anemia and thrombocytopenia and recombinant thrombomodulin for treating DIC, the main principle of DIC management is the appropriate treatment of the causative disease." (PMID 39165681, 2024). "When organs from pigs expressing a human coagulation‐regulatory protein, for example, thrombomodulin, have been transplanted into baboons, we have not seen thrombocytopenia of this degree when tocilizumab and etanercept have been administered together." (PMID 35049144, 2022).
venous thromboembolism (5 papers, 2012 to 2026). Occlusion of the lumen of a vein by a thrombus that has migrated from a distal site via the blood stream. "Previous studies displayed that thrombomodulin gene polymorphisms are closely associated with venous thromboembolism (VTE), while the results are inconsistent." (PMID 33725974, 2021).
allergic disease (4 papers, 2013 to 2021). An immune response that occurs following re-exposure to an innocuous antigen, and that requires the presence of existing antibodies against that antigen. "Major basic protein, eosinophilic cationic protein activates platelets and promotes thrombus formation by inhibiting thrombomodulin in hypereosinophilic syndromes and allergic diseases." (PMID 28352439, 2013). "Although all samples sequenced in this experiment were THBD (BDCA3)-positive DCs, the expression of THBD was significantly higher in DCs from patients with allergies than control DCs." (PMID 33207814, 2020).
chronic kidney disease (4 papers, 2018 to 2025). Impairment of the renal function secondary to chronic kidney damage persisting for three or more months. "In the studied group of children with chronic kidney disease, thrombomodulin correlated significantly with another mediator of endothelial injury—ADMA." (PMID 29682152, 2018). "Moreover, GPA patients with chronic kidney disease were characterized by higher thrombomodulin level (11.7 [9.4–17.6) vs. 5.4 [4.4–6.9] ng/ml, p < 0.001) and VCAM-1 level (1258.2 [893.2–1457.7] vs. 747.4 [546.9–917.5] ng/ml, p < 0.001)." (PMID 29850964, 2018). "GPA patients with chronic kidney disease also had increased levels of VCAM-1, thrombomodulin and IMT." (PMID 29850964, 2018).
glioblastoma (4 papers, 2012 to 2025). The most malignant astrocytic tumor (WHO grade IV). "Moreover, a high proportion of THBD+ cells correlates with poor prognosis in glioblastoma (GBM) patients." (PMID 38809929, 2024).
hyperhomocysteinemia (4 papers, 2010 to 2025). A serious metabolic condition caused by mutations in the MTHFR gene, medications, or nutritional deficiency. "Moreover, hyperhomocysteinemia has been implicated in downregulation of thrombomodulin expression, an essential endothelial anticoagulant protein that activates protein C, thereby tipping the hemostatic balance toward thrombosis." (PMID 40981125, 2025).
metabolic syndrome (4 papers, 2016 to 2025). A cluster of metabolic risk factors for CARDIOVASCULAR DISEASES and TYPE 2 DIABETES MELLITUS. "Vascular pathology has previously been observed in patients with depressive symptoms and another study observed that thrombomodulin levels significantly increased with elevated metabolic syndrome load." (PMID 26613755, 2016).
C3 glomerulopathy (3 papers, 2019 to 2024). "In TMA, especially in aHUS, and C3 glomerulopathy, genetic sequencing studies have contributed to the identification of genetic variants involved in the complement pathways, such as: CFH, CFI, MCP/CD46, complement factor B (CFB), thrombomodulin (THBD), C3 and others." (PMID 39780910, 2024).
cerebral malaria (3 papers, 2019 to 2023). A sequestration of Plasmodium falciparum in the brain, which can cause coma and/or seizures. "DF has been also proposed for the treatment of thrombosis associated with various pathologies, including cerebral malaria, in which DF treatment leads to the maintenance of thrombomodulin and the suppression of platelet aggregation." (PMID 31649666, 2019). "Laboratory findings demonstrate that plasma D-dimer levels, fibrin degradation products, fibrinogen monomers, and soluble thrombomodulin are elevated in children with cerebral malaria, indicating a hypercoagulable stage." (PMID 37368707, 2023).
diabetic nephropathy (3 papers, 2016 to 2022). "Loss of thrombomodulin-dependent APC formation interrupts crosstalk between the vascular compartment and podocytes, causing glomerular apoptosis and diabetic nephropathy." (PMID 34485320, 2021).
falciparum malaria (3 papers, 2006 to 2021). "Unfortunately the intestinal blood vessels, another favoured site for sequestration in falciparum malaria, were not included in either the CD36 or the thrombomodulin study." (PMID 17029647, 2006).
gastric cancer (3 papers, 2012 to 2024). A primary or metastatic malignant neoplasm involving the stomach. "The present study investigated the roles of extracellular HMGB1 in the progression of gastric cancer (GC) and the therapeutic effects of recombinant human soluble thrombomodulin (rTM) targeting HMGB1." (PMID 35328684, 2022). "Nevertheless, we found significantly higher levels of THBD DNA methylation in CRC than in gastric cancer (p<0.001)." (PMID 23209692, 2012).
Hyperglycemia (3 papers, 2011 to 2022). An increased concentration of glucose in the blood. "Findings from this study reveal that on admission to ICU, critically ill patients with hyperglycemia display elevated circulating levels of sRAGE, HMGB-1 and soluble thrombomodulin." (PMID 21871056, 2011).
lung disease (3 papers, 2017 to 2025). "In IIM, cohort studies have demonstrated higher levels of circulating VCAM-1, ET-1, thrombomodulin, and plasminogen activator inhibitor-1 in IIM patients with ILD compared to IIM without lung disease." (PMID 40055821, 2025).
lupus nephritis (3 papers, 2018 to 2023). Glomerulonephritis in the context of systemic lupus erythematosus. "To further elucidate the predictive value of thrombomodulin in pSLE renal involvement, we used the ROC curve to analysis our biomarkers as well as anti-dsDNA, an autoantibody with great correlation with the presence of lupus nephritis." (PMID 31651352, 2019). "Comparison of syndecan-1, hyaluronan, thrombomodulin and VCAM-1 as putative biomarkers for lupus nephritis compared to conventional serological and clinical markers of disease." (PMID 37854589, 2023).